INS (insulin)
Diseases named in the same sentence as INS in open-access papers (continued):
Sharing a sentence is not in itself a finding about the gene and the disease.
prediabetes (continued). "While women of reproductive age tend to be more insulin sensitive, less prone to store fat in visceral and ectopic compartments, and have a greater capacity to secrete insulin and incretins, postmenopausal women are at higher risk for central obesity, hypertriglyceridemia, and prediabetes." (PMID 40299427, 2025). "The clustering and timeline analysis of high-frequency keywords and co-cited references in this study may help researchers understand that the hotspots of prediabetes research are insulin sensitivity and intervention and prevention of high-risk diseases in prediabetes." (PMID 38241546, 2024). "Similarly, the requirement of insulin therapy during pregnancy, ethnicity, gravidity, BMI, weight at the time of delivery, and neonatal weight are other factors that have been shown to be associated with the risk of prediabetes." (PMID 37767000, 2023). "Therefore, breakfast consumption might be effective in modulating insulin sensitivity and secretion and reducing the risk of prediabetes." (PMID 36909337, 2023). "An American cross-sectional analysis from 2005 to 2016 indicated that the prevalence of prediabetes among adolescents was 18.0%, linked to higher BMI, low-density lipoprotein cholesterol levels, systolic blood pressure, and central adiposity and lower insulin sensitivity." (PMID 36079871, 2022). "While tomosyn inhibitors would seemingly be attractive therapeutics to increase insulin-stimulated glucose uptake by muscle, the potential for elevation of basal glucose uptake, causing hypoglycemia, would require careful consideration as a therapeutic target for prediabetes and T2D." (PMID 35774142, 2022). "Indeed, it has been shown that in people with prediabetes with relatively high fasting insulin, a low-fat diet is most effective for weight loss, whereas for people with prediabetes with relatively low fasting insulin, a low-carbohydrate diet is most effective." (PMID 35327447, 2022). "However, NOD mice prediabetes often show variable insulin sensitivity which is significantly impacted by the loss of insulin secretion and so it is difficult to ascertain in the present study whether the effects of ALT on insulin, are beneficial." (PMID 34203471, 2021). "Second, while this study confirms that exercise based on ACSM dose recommendations can improve prediabetes-related blood glucose and insulin resistance, the heterogeneity of the original trials limited the derivation of an ‘optimal’ prescription." (PMID 41334726, 2026). "He presented with prediabetes (HbA1c of 5.8%) and elevated insulin and C-peptide levels, 398 pmol/L and 1475 pmol/L, respectively." (PMID 41516406, 2026). "Distinct insulin‐related metabolic features and sex identify different phenotypes with distinct lipidome profiles, highlighting the need to place prediabetes in a broader context of metabolism beyond glucose." (PMID 41133433, 2026). "In the present study, vildagliptin treatment for 4 weeks effectively alleviated prediabetes and hyperlipidemia, as indicated by decreases in plasma insulin, HOMA index, plasma total cholesterol, and plasma low‐density lipoprotein levels." (PMID 41566690, 2026). "Together, these findings identify OAS as a glucose-dependent insulin secretagogue with therapeutic potential to enhance insulin secretion and prevent progression from prediabetes to T2D." (PMID 41718459, 2026). "Our meta-analysis revealed that exercise interventions can enhance glucose metabolism and insulin resistance in individuals with prediabetes." (PMID 41334726, 2026). "In this study, we found that MIAE significantly improved SM metabolism, glucose control, and insulin sensitivity in individuals with prediabetes, as assessed by MRI parameters and standard metabolic markers." (PMID 41428169, 2025).
prediabetes (continued). "By performing these ROB2 and GRADE analyses, we can also provide more confidence in presenting the roles of vitamin D supplementation in ameliorating the insulin sensitivity and metabolic health in people with prediabetes." (PMID 40004770, 2025). "Moreover, a notable strength of this study is that it provides novel insight to how exercise may affect neuronal insulin signaling in relation to peripheral insulin sensitivity among a clinically relevant group of older adults with prediabetes who at risk for ADRD." (PMID 39421964, 2025). "Gal-4 facilitates the transport of dipeptidyl peptidase-4 (DPP-4) to the intestinal epithelium, leading to decreased incretin activity and contributing to impaired insulin secretion, prediabetes and its cardiometabolic complications." (PMID 41226378, 2025). "In consistency, for participants with prediabetes, even in the insulin‐compensated state, higher 1‐h Grem2 levels were associated with better β‐cell function indicated by the oral DI independent of age, sex, and adiposity before calorie restriction." (PMID 40270326, 2025). "Exercise-evoked proteomic alterations in muscle of subjects with prediabetes are of great importance for the study of relationships between insulin resistance and exercise." (PMID 40775511, 2025). "Alternatively, resistance training promotes the rapid enhancement of skeletal muscle oxidative capacity, insulin sensitivity, and glycemic control in adults with prediabetes." (PMID 40005307, 2025). "Individuals with lower central sensitivity to thyroid hormones often exhibit higher serum FT4 levels, potentially reducing the likelihood of developing prediabetes by enhancing insulin sensitivity and glucose utilization." (PMID 40600010, 2025). "Inflammation and oxidative stress are critical factors in prediabetes, disrupting insulin signaling and promoting metabolic dysfunction." (PMID 40004770, 2025). "Some interventions such as metformin are effective in reducing fasting insulin and IR in children and adolescents with clinical IR or prediabetes." (PMID 40365140, 2025). "Conversely, prediabetes emerges when β-cells fail to secrete sufficient insulin to maintain normal glucose levels." (PMID 40162315, 2025). "Two studies analysed patients with NCPHPT and prediabetes: fasting plasma glucose was higher in patients with NCPHPT and prediabetes vs. controls with prediabetes, but similar HbA1c, fasting insulin levels, HOMA-IR, HOMA-B%, as well as OGTT." (PMID 40283231, 2025). "The elevated level of S100B in the PD group can be attributed to the fact that individuals with prediabetes often experience intermediate insulin resistance, chronic inflammation and metabolic dysfunction." (PMID 41296388, 2025). "IR leads to increased insulin demand, and when β-cells fail to compensate, glucose levels begin to rise, marking the transition from normoglycemia to prediabetes and eventually T2D." (PMID 40162315, 2025). "Short‐term exercise training lowered fasting pro‐BDNF and increased glucose‐stimulated total Akt derived from neuronal extracellular vesicles (nEVs) in relation to peripheral insulin sensitivity among older adults with prediabetes." (PMID 39421964, 2025). "Prediabetes is an early stage of impaired glucose and insulin responses, and a critical period for dietary strategies to improve metabolic health." (PMID 40689342, 2025). "Insulin was correlated with testosterone, antral follicle count, and ovarian volume only in prediabetes group (p<0.05)." (PMID 41384021, 2025). "Results of the mediation analyses for direct and indirect effects of insulin on total testosterone in prediabetes group." (PMID 41384021, 2025). "In conclusion, daily consumption of mango for 24 weeks improved both short- and long-term blood glucose control, reduced insulin resistance, enhanced insulin sensitivity, and promoted favorable changes in body composition among individuals with prediabetes." (PMID 40941087, 2025).
prediabetes (continued). "In prediabetes, increased ROS production occurs due to insulin resistance and excess glucose, but the adaptive response of the antioxidant system (enzymatic and non-enzymatic) is relatively weakened during this period." (PMID 41614781, 2025). "While purified anthocyanins have improved HbA1c and insulin sensitivity in prediabetes, a meta-analysis found greater HbA1c reductions from fruit powder-derived anthocyanins, indicating synergistic actions among bioactive elements." (PMID 41154567, 2025). "High insulin levels found in prediabetes and early T2D can stimulate thyroid tissue hyperplasia, leading to thyroid enlargement and nodule formation." (PMID 40731899, 2025). "Previously, a substantial role of detriment in insulin secretion in prediabetes and at the beginning of manifested T1D was reported, mainly in the pediatric population." (PMID 40004639, 2025). "As a major tissue in both insulin-stimulated and insulin-independent (exercise-evoked) uptake and metabolism of plasma glucose, its role in prediabetes prevention and its reversal cannot be overlooked." (PMID 40775511, 2025). "Both decreased insulin sensitivity (DIS) and decreased beta-cell function (DBCF) were significantly associated with progression to prediabetes and T2D (all P < 0.001) according to both the unstandardized and standardized analyses." (PMID 41561051, 2025). "Prediabetes is a condition arising from insufficient production of insulin in the pancreas to maintain normal blood glucose levels." (PMID 41165062, 2025). "The hallmarks of prediabetes and type 2 DM are gradual changes in insulin synthesis and secretion from the pancreas and alterations in insulin action in the liver, adipose tissue, and skeletal muscle." (PMID 40321607, 2025). "Myocardial energy status was lower in the volunteers with prediabetes (PCr/ATP 1.03 ± 0.08) compared to non‐insulin resistant overweight or obese volunteers (PCr/ATP 1.22 ± 0.04, p < 0.05), but FFA were not significantly different between groups." (PMID 40013525, 2025). "While high-intensity training effectively enhances insulin sensitivity and endothelial function, additional clinical trials are needed to determine optimal intensity levels for different health outcomes in prediabetes patients." (PMID 41377666, 2025). "In our study, the IR were only mildly elevated in the prediabetes group, and serum insulin levels were similar between the groups." (PMID 41384021, 2025). "Previous studies have demonstrated that bacterial butyrate production and the number of butyrate-producing bacteria are decreased in individuals with prediabetes and that supplementation with butyrate can improve insulin sensitivity." (PMID 41394123, 2025). "Results showed that in males with prediabetes, eTRF reduced blood pressure, oxidative stress, insulin sensitivity, and insulin levels, even though food intake was the same as that in the control group, and no weight loss occurred." (PMID 38998465, 2024). "A 2023 meta-analysis reported a reduction in postprandial blood glucose following supplementation with resistant starch types 1 and 2, and a decrease in postprandial insulin response with resistant starch type 2 (RS2) in patients with T2DM or prediabetes." (PMID 39458444, 2024). "Thiazolidinediones (TZDs), such as troglitazone, rosiglitazone, and pioglitazone, which act as PPARγ agonists, are employed to enhance the peripheral insulin sensitivity in individuals with diabetes and prediabetes." (PMID 39201522, 2024). "The efficacy of vitamin D on glycemic stability and insulin function was also found in patients with prediabetes." (PMID 38650715, 2024). "The remaining two studies found that diabetic therapies such as Exenatide or a combination of Metformin and Exenatide achieve better insulin sensitivity and a higher rate of remission of prediabetes compared to Metformin alone among women with PCOS." (PMID 39479136, 2024).
prediabetes (continued). "As an essential component of lifestyle interventions, exercise interventions have been shown to aid the benign regression of prediabetes by improving insulin resistance, blood glucose levels, lipid metabolism, inflammatory response, and gut flora." (PMID 38440785, 2024). "Recent research has highlighted the TyG Index’s efficacy in predicting and evaluating prediabetes, surpassing insulin-dependent indices like HOMA-IR, and it serves as a valuable screening tool for investigating IR." (PMID 39010858, 2024). "This study aimed to investigate the effects of a once-daily beverage containing Tremella fuciformis (snow mushroom) on anthropometric measurements, metabolic biomarkers, and insulin sensitivity in overweight/obese subjects with prediabetes." (PMID 38439104, 2024). "Interactions of micronutrients and lipids with prediabetes, poor insulin secretion, and glycemic indices." (PMID 39055387, 2024). "Reduced adiponectin and nefastin-1 levels in prediabetes were associated with an increased risk of developing DM, whilst leucine-rich alpha-2-glycoprotein 1 (LRG1) expression was related to insulin dysmetabolism." (PMID 38667278, 2024). "The early stages of developing prediabetes are defined by alterations in pancreatic beta-cell secretion of insulin and reduced insulin sensitivity at the cellular level." (PMID 39726936, 2024). "Lipocalin-2 silencing results in a worse outcome in obese mice, while its increase improves insulin and glucose homeostasis, elucidating the physiological protective mechanisms of this hormone against prediabetes." (PMID 38667278, 2024). "The objective of this study was to assess the impact of Tremella fuciformis beverage consumption on body measurements, metabolic biomarkers, and insulin sensitivity in overweight and obese subjects with prediabetes." (PMID 38439104, 2024). "In their study, a 5-week intervention of eTRE in male individuals with prediabetes resulted in substantial improvements in insulin levels, insulin sensitivity, blood pressure, and oxidative stress levels." (PMID 38520010, 2024). "Insulin resistance with subsequent insulin hypersecretion and impaired incretin action is critical in the pathophysiology of prediabetes." (PMID 39070421, 2024). "OS and chronic inflammation play roles in IR, impaired insulin secretion, prediabetes, and diabetes." (PMID 38989199, 2024). "We determined the effect of linagliptin/metformin (LM) vs metformin (M) on GM composition and its relationship to insulin sensitivity (IS) and pancreatic β-cell function (Pβf) in patients with prediabetes." (PMID 38678119, 2024). "Insulin resistance (IR), characterized by impaired peripheral insulin activity, represents a critical state in prediabetes pathogenesis." (PMID 38667278, 2024). "This cluster mainly comprises proteins involved in lipid metabolism, BCAA catabolism, and oxidative stress responses, reflecting significant metabolic alterations in prediabetes that impact insulin sensitivity and overall metabolic homeostasis." (PMID 39085321, 2024). "In mice affected by high-fat diet-induced prediabetes, the calorie-restricting dietary regimen ameliorated glucose metabolism and Cx36 gap junction alterations, Ca2+-mediated mechanisms, and insulin secretion." (PMID 38667278, 2024). "Taken together, these studies indicate that TRE can be effective in improving glucose homeostasis in healthy older adults and insulin sensitivity in patients with prediabetes independently of caloric restriction." (PMID 39584020, 2024). "The prediabetes group had higher levels of post-load 2-h PG and insulin, and a lower level of HDL cholesterol than the NGT group." (PMID 39403586, 2024). "The glucose tolerance curve reflects both the defects in insulin secretion and insulin sensitivity that have been described in patients with prediabetes." (PMID 38397965, 2024).
prediabetes (continued). "The MIRG proxy suggested increased pancreatic insulin release in the obese groups, which is consistent with prediabetes in humans and insulin dysregulation in horses, as beta cells initially produce excessive insulin in order to reduce blood glucose." (PMID 38886475, 2024). "The coexistence of IGF and IGT, elevated HbAc1 levels, insulin resistance, reduced insulin sensitivity, and increased beta cell function in our PD group indicated the induction of prediabetes at 36 weeks." (PMID 38791468, 2024). "Prebiotics induce beneficial changes in gut microbiota composition in prediabetes, while postbiotics can enhance gut barrier function, complementing each other to improve glucose metabolism and insulin sensitivity." (PMID 39064648, 2024). "Physical activity can help to slow down the progression of disease in individuals with prediabetes by increasing glucose uptake and utilization, improving insulin sensitivity, and protecting pancreatic β-cell function." (PMID 38919473, 2024). "The induction of prediabetes was confirmed with impaired insulin and tolerance to glucose, a rise in the fasting plasma glucose, and a rise in the visceral adipose tissue mass." (PMID 39070421, 2024). "Prediabetes is related to resistance to insulin and malfunctioning of β-cells, both of which generally tend to occur before the glucose abnormalities are detected." (PMID 39070421, 2024). "This suggests that AdEVs play a role in priming β-cells for increased insulin secretion, potentially aiding in maintaining normal glucose levels during the early stages of prediabetes." (PMID 39698417, 2024). "It has been repeatedly shown that an acute bout of resistance exercise improves insulin sensitivity and glycemic control during at least the following 24 hours in individuals living with prediabetes and T2D." (PMID 39499920, 2024). "Insufficient sleep or waking up at inappropriate times can reduce insulin secretion and disrupt glucose metabolism, leading to prediabetes in obese individuals." (PMID 39716153, 2024). "In summary, aerobic exercise protects individuals with prediabetes by improving insulin sensitivity and metabolic functions, making it a promising intervention for managing prediabetes." (PMID 39859972, 2024). "Women taking Exenatideor combination therapy achieved higher rates of prediabetes remission compared to those only taking Metformin, by enhancing postprandial insulin secretion." (PMID 39479136, 2024). "Glucose and insulin biomarkers are key indicators of T2DM risk, and their use is crucial in identifying and addressing prediabetes in youth populations through lifestyle modifications." (PMID 39519417, 2024). "Along with insulin signaling, other deregulated hormonal pathways are involved in prediabetes pathogenesis." (PMID 38667278, 2024). "In keeping with the present data, a previous study reported a greater impairment in insulin sensitivity assessed by euglycemic hyperinsulinemic clamp in women with prediabetes than men when compared with their NGT counterparts." (PMID 38671460, 2024). "Our new detailed analysis shows that increased fasting total GLP-1 is observedwith male sex, increased adiposity and liver fat, and decreased insulin sensitivityparticularly in the prediabetes population." (PMID 38686701, 2024). "Improving insulin sensitivity and β-cell function has revealed to be beneficial for prediabetes stabilization and reversion from prediabetes to normoglycemia." (PMID 37715242, 2023). "In participants with prediabetes, long-term almond consumption showed adverse effects on insulin sensitivity and glucose metabolism." (PMID 37258943, 2023). "This allows metabolic homeostasis to be maintained in the early stages of the disease; this compensatory insulin phase is called prediabetes and can last for years." (PMID 37873836, 2023). "Physical exercise is the first-line intervention for prediabetes, and metformin is the most widely used oral insulin-sensitizing agent." (PMID 37899436, 2023).